NPIPA8 (nuclear pore complex interacting protein family member A8)
Synonyms: LCR16a9; NPIPA7
Tractability: No criterion of Open Targets' tractability assessment is met for any kind of drug.
Gene: Protein-coding gene on chromosome 16 (18,317,919 to 18,336,736, reverse strand). Ensembl gene ENSG00000214940.
Subcellular location (Human Protein Atlas): Nucleoplasm
Homologues: Paralogues in human: NPIPA7 (100% identical), NPIPA6 (99% identical), NPIPA9 (99% identical), NPIPA1 (93% identical), NPIPA5 (93% identical), NPIPA2 (88% identical), NPIPA3 (88% identical), NPIPB2 (72% identical), NPIPB12 (70% identical), NPIPB13 (70% identical), NPIPB4 (70% identical), NPIPB5 (70% identical), and 7 more.
Diseases named in the same sentence as NPIPA8 in open-access papers:
NPIPA8 is named in the same sentence as 5 diseases in open-access papers, as found by Europe PMC text mining. Sharing a sentence is not in itself a finding about the gene and the disease.
NPIPA8 shares sentences with these, for which no sentence is quoted: breast carcinoma (1 paper); cancer (1); colorectal cancer (1); lung carcinoma (1); prostate carcinoma (1).